CCND1 (cyclin D1)
Diseases named in the same sentence as CCND1 in open-access papers (continued):
Sharing a sentence is not in itself a finding about the gene and the disease.
cancer (continued). "The relationship between ASPM and CDK4 or CCND1 and the related mechanism should be further explored, and perhaps the role and the mechanism are different in different kinds of cancers." (PMID 32742488, 2020). "The activation of Wnt/β-catenin signaling in cancer plays a central role in the cell cycle and contributes to the neoplastic transformation through two of its main downstream targets, c-Myc and Cyclin D1." (PMID 32824207, 2020). "Existing studies have reported the regulatory mechanism of Bcl-2 and CCND1 in cancer cells, including the post-transcriptional downregulation by miR-15 and miR-16." (PMID 33490079, 2020). "A new role for Cyclin D1 in controlling liver cell proliferation and cancer stem cells self-renewal is rapidly emerging." (PMID 33317149, 2020). "Fucoidan increased cell death in several cancers by inhibiting the activation of cyclin D1, cyclin E, cyclin-dependent-kinases (Cdks), PI3K, and MAPK." (PMID 31936539, 2020). "Like cyclin D1, Pin1 has been reported to be overexpressed in various cancers, including breast, colon, liver, and lung cancers." (PMID 31884567, 2020). "In the second stage, the expression levels turned out to be similar in cancer versus normal blood for most genes, except for CDK18 and CCND1 which paradoxically turned out to be downregulated in cancer blood." (PMID 32013938, 2020). "In this study, RPE not only inhibited cyclin D1 and c-myc expression under basal conditions for A549 cells, but also suppressed cancer growth under artificial EGF-treated conditions." (PMID 33158043, 2020). "Knocking down DILA1 decreases Cyclin D1 protein expression, inhibits cancer cell growth and restores tamoxifen sensitivity both in vitro and in vivo." (PMID 33139730, 2020). "Cyclin D1 through its binding partners CDKs is a key regulator of the cell cycle and is overexpressed with high frequency in many human cancers." (PMID 33317149, 2020). "Not only in NSCLC but also in other types of cancer the depletion of PTEN is significantly correlated with increased Cyclin D1 expression." (PMID 33317149, 2020). "VEGFA, PTEN, PIP5K1A, CDK1, and CCND1 in the panel are key factors involved in the PI3K/AKT pathways important for cancer survival and metastasis." (PMID 33363151, 2020). "Counterintuitively, CCND1 was downregulated in 23% of carcinomas, more frequently in HPV-positive samples." (PMID 32224897, 2020). "Our results suggest the overexpression of Akt1 and 2 with respect to migration and expression of Bcl-2, cyclin D1, and survivin proteins, which are important for cancer cell survival and proliferation." (PMID 31252679, 2019). "Cyclin D1 (coded by CCND1 gene) is an oncoprotein overexpressed in about 50% HBCs and associated with cancer onset and progression due to its role in cell cycle initiation." (PMID 31461477, 2019). "Dysregulation of this pathway leads to the activation of proto-oncogenes (c-MYC) and cyclin-dependent kinases (Cyclin D1), which eventually leads to cancer cell proliferation." (PMID 31783627, 2019). "The activation of the Wnt/β-catenin signaling influences the proliferation of cancer cells by affecting the expression of cMYC and cyclin D1." (PMID 31766223, 2019). "Cyclin D1 is an oncogene frequently overexpressed in human cancers that has a dual function as cell cycle and transcriptional regulator, although the latter is widely unexplored." (PMID 31384172, 2019). "Overexpression of CCND1 disrupts the normal cellcycle, possibly promoting the development and progression of cancer." (PMID 31131003, 2019).
cancer (continued). "Cyclin D1 is frequently overexpressed in human cancers and it is regarded as an oncogenic driver in the majority of these cancers." (PMID 30899002, 2019). "Ccnd1 has an important role in cell cycle regulation, and overexpression induces the formation of different cancer types." (PMID 31815961, 2019). "Here, we demonstrate that cyclin D1 stability is positively regulated with O-GlcNAcylation levels in human cancer cells." (PMID 30853938, 2019). "Apart from cyclin D1, cyclin E is also extensively studied in many cancers like carcinomas (breast, lung cervix, endometrium, and GI tract), lymphoma, leukemia, sarcomas and adrenocortical tumors." (PMID 30741976, 2019). "Inhibitors of cyclin D1/Cdks 4/6 complexes have been explored as therapeutic targets as this checkpoint was found deregulated in several human cancers." (PMID 31827691, 2019). "To conclude, this study provides new insights into the positive regulation of cyclin D1 stability by O-GlcNAcylation and opens new perspectives on the contribution of hyper-O-GlcNAcylation to the deregulation of cell proliferation in cancer." (PMID 30853938, 2019). "Here, the authors show that the absence of SMARCA4/2 reduces chromatin accessibility at the CCND1 locus, leading to a subsequent reduction in cyclin D1 expression, which promotes vulnerability of these cancers to CDK4/6 inhibition." (PMID 30718506, 2019). "This interpretation has supporting evidence: ERK1/2 played a crucial role in TRX-1-mediated cell proliferation through the regulation of cell cycle modification with cyclin D1, which is a target of β-catenin/Tcf-dependent transcription in cancer cells." (PMID 31743979, 2019). "Ectopic expression of ISL1 induced cyclin D1, cyclin B, and c-Myc expression in GC cells, which have been previously shown to be involved in cancer cell proliferation in vitro." (PMID 30674889, 2019). "Our findings reveal a molecular basis for cancer therapy through targeting glutaminolysis and mitochondrial respiration in ESCC with dysregulated Fbxo4-cyclin D1 axis as well as cancers resistant to CDK4/6 inhibitors." (PMID 30899002, 2019). "For example, nuclear pAMPK increased transcription of pro-cancerous molecules, such as cyclin D1, c-myc, and Oct4, in cancer cells under metabolic stresses (e.g., in glucose-deprived conditions)." (PMID 31640193, 2019). "To better understand the cascade of signaling events we also demonstrate that EP modulates AKT, with subsequent reduction of proteins involved in cancer cell survival, proliferation, and progression (e.g., Cyclin D1, c-Myc)." (PMID 30837881, 2019). "We also found that the hub genes (e.g., MAPK8, EGF, FALGDS, CCND1, MYC) in this network have been linked to cancer in wide literature reports." (PMID 31080457, 2019). "Pharmacological inhibition of USP2 accelerates cyclin D1 degradation and leads to cell cycle arrest in several cancer cell lines among which the HCT116 colon cancer cell line and MCF7 breast cancer cell line." (PMID 30853938, 2019). "It has been proposed to be an oncogene with a significant role in cancer progression, inducing up-regulation of cyclin D1 via GSK3beta/beta-catenin pathway, leading to the acceleration of the cell cycle." (PMID 31234367, 2019). "The suppression of the STAT3 signaling pathway, which targets both CCND1 and Bcl-2, led to down-regulation of the expression of both proteins, thereby inducing cellular apoptosis in cancer cells." (PMID 31718693, 2019). "Other target genes in our study including ADCY1, BCL2, BDKRB2, CALM1, and CCND1 have been proved to play important roles in multiple pathways of cancer progression." (PMID 31775867, 2019).
cancer (continued). "Cyclin D1 is also frequently deregulated in cancer and is a biomarker of cancer phenotype and disease progression." (PMID 30885146, 2019). "We suggested that Fx administration suppressed the development of subcutaneous tumors, engrafted cancer stem-like Csps, along with Cyclin D1 suppression in BALB/c nu/nu mice." (PMID 30705512, 2019). "Two gain regions contained the well-known oncogenes EGFR (7p11.2) and CCND1 (11q13.3) and several known cancer suppressor genes, such as FHIT (3p14.2–p12.1), FAT1 (4q35.1), CDKN2A (9p21.3), and ATM (11q22.3–q24.3), reside within the 10 deletion regions." (PMID 31159251, 2019). "This process initiates the transcription of downstream genes (e.g., CD44, VEGF, c-Myc, and cyclin D1), leading to the proliferation of cancer cells and occurrence and development of tumors." (PMID 31827404, 2019). "The most initially identified targets for β-catenin are c-myc and cyclin D1, which act as oncogenic roles in cancer development." (PMID 31431517, 2019). "The stabilisation of β-catenin translocated to the nucleus and interacted with TCF/LEF transcription factors to activate target genes including cyclin D1 and c-Myc, and to promote cancer progression." (PMID 30787268, 2019). "It was shown that apocynin inhibited cancer cell proliferations via down-regulating cyclin D1 and inhibiting Rac1 phosphorylation, one component of the NOX complex." (PMID 31551769, 2019). "The CyclinD1 over-expression due to the mutation, amplification and rearrangement of the CCND1 gene is commonly detected in different types of malignant tumors." (PMID 31590696, 2019). "Cyclin D1 had been reported to be highly expressed in cancers of various origins, such as breast, esophageal, colon, and bladder." (PMID 31409760, 2019). "Cyclin D1 and p16 are molecules with pivotal roles in cell cycle control and the development of diverse human cancers." (PMID 31168343, 2019). "Consistent with its positive effect on cell cycle progression, cyclin D1 is a proto-oncogene frequently overexpressed in many cancers." (PMID 30885146, 2019). "Clearly, there is much more that needs to be done to fully elucidate the mechanism by which Obatoclax mediates the inhibition of cyclin D1 in cancer cells." (PMID 30875757, 2019). "In fact, CDK4/6 and CCND1 form together a complex, which regulates cell cycle and has been for that reason covered in various cancer studies." (PMID 30976209, 2019). "Recently studies on developing CDK inhibitors to treat cancer have focused on palbociclib, abemaciclib, and ribociclib, which are selective CCND1/CDK4/6 inhibitors." (PMID 31349793, 2019). "CCND1 is a key cell-cycle regulator and one of the most importantoncogenes, being overexpressed in several human cancers." (PMID 31131003, 2019). "The Specificity Protein 1 (SP1) transcription factor has been shown to contribute to the CYP1B1 mediated increase of growth regulatory genes like cyclin D1 as well as the proliferation, migration and invasion of cancer cells." (PMID 31370872, 2019). "Both QC and QS inhibited the proliferation and migration of primary cancer hepatocytes by reducing cyclin B1, cyclin D1 and N-cadherin expression and increasing E-cadherin expression." (PMID 30723284, 2019). "As an important cell cycle driver, cyclinD1 encoded by CCND1 is a prognostic and predictive factor in cancers." (PMID 31934637, 2019). "Previously, SOX9 has been reported to positively regulate β‐catenin expression in the canonical Wnt pathway and downstream effectors such as Cyclin D1 and c‐Myc for regulating cancer progression." (PMID 31402556, 2019).
cancer (continued). "Targeting the cognate catalytic CDKs of cyclin D1 is regarded as a feasible way to treat human cancers." (PMID 30899002, 2019). "Akin to our findings with IL11‐Mutein therapy, tumors from bazedoxifene‐treated mice had reduced expression of the pro‐survival protein Bcl‐xL, of the proliferative marker cyclin D1 and the cancer cell‐specific mitosis marker survivin." (PMID 30885958, 2019). "Cyclin D1 encoded by the CCND1 gene is one of the frequently altered and overexpressed cell cycle regulators in cancers." (PMID 31262974, 2019). "Cyclin D1, and to a lesser extent the other D-type cyclins, is deregulated in cancer and is a biomarker of cancer phenotype and disease progression." (PMID 30885146, 2019). "The Wnt/β-catenin signaling pathway activates transcription of many genes involved in cancer cell proliferation, including cell cycle regulated gene cyclin D1." (PMID 31608135, 2019). "We previously reported that tNOX knockdown in T24 cells reversed cancer phenotypes in association with downregulation of SIRT1 and cyclin D1, even though the details of the underlying mechanism remained unclear." (PMID 31635402, 2019). "In response to mTOR inhibition, however, cyclin D1 is elevated by everolimus in various types of cancer." (PMID 31388935, 2019). "Further, upon force-feeding of MM cancer exosomes to cancer cells, we see significant decreases in miR-16-5p target oncogenic protein CCND1." (PMID 31406207, 2019). "In tumor cell lines and cancer patients, two major isoforms of CCND1 have been identified: CCND1a, which contains exons 1–5, and CCND1b, which ends with a longer exon 4 and is created by CR-APA using poly(A) sites within intron 420–23." (PMID 29717174, 2018). "Cyclin D1 has prognostic significance through its function in cancer cell proliferation, and also plays an essential role in recruiting transcription factors such as E2F1 and regulates gene transcription via inhibition of p30041,42." (PMID 30054560, 2018). "It has been reported that FOXM1 enhances cancer cell growth through upregulating the cell cycle-related genes cyclin B1 and cyclin D1." (PMID 29552295, 2018). "Effect of satureja khuzestanica extract (SKE) on cyclin D1 protein level as a marker of cell proliferation in MCF-7 cancer cells." (PMID 29755565, 2018). "Recently, Sun’s work suggested that cyclin D1 is required for miRNA let-7-induced cancer repression and the cell death." (PMID 30279365, 2018). "We previously revealed that clioquinol combined with zinc treatment promoted apoptosis and down-regulated cyclin D1 protein levels in cancer cells." (PMID 29678153, 2018). "Down-stream effects of SHetA2 binding to these proteins lead to degradation of cyclin D1 in both normal and cancer cells and Bcl-2 and Bcl-xl in cancer cells only." (PMID 29634717, 2018). "Exome studies containing CCND1 amplification with respective cancer type and CCND1 amplification frequency." (PMID 29969496, 2018). "A repeated measures ANOVA with Dunnett correction for multiple comparisons indicated that the cancer cell lines exhibited significantly greater cyclin D1 reduction compared to IOSE (p < 0.05)." (PMID 29273857, 2018). "TY-NS-B inhibited the cell proliferation in the various cancer cells and downregulated cyclin D1 protein level." (PMID 29925351, 2018). "Overexpression of cyclin D1 is observed in a variety of human cancers and is involved in tumorigenesis." (PMID 30428594, 2018).
cancer (continued). "Further studies revealed that the compounds were able to induce cancer cell differentiation and concomitantly downregulate cyclin D1 expression with upregulation of p27 levels, consistent with cell cycle arrest at the G1 phase." (PMID 30374056, 2018). "Peaks involving important cancer genes such as CCND1, EGFR, ERBB2, FGFR1, AKT1, MYC, KRAS and CDKN2A/2B, which were confirmed in our data." (PMID 30131072, 2018). "Among the cyclin types, cyclin D1 has been observed to be overexpressed in human cancer and cyclin D1-CDK4/6 complex induces the phosphorylation of the retinoblastoma protein, resulting to inducing G1/S transition." (PMID 29554905, 2018). "FOXO3a has been implicated in cell cycle arrest leading to growth inhibition via upregulation of p21, p27 and downregulation of Cyclin D1 in various cancers." (PMID 30123091, 2018). "Downregulation of ARE-BPs is observed in cancers, leading to stabilization of mRNA targets involved in the cell cycle (cyclin D1, for example), in angiogenesis (VEGF, for example), or in apoptotic resistance (BCL2, for example)." (PMID 29495341, 2018). "Deregulation of mRNA export key factor expression occurs in many types of cancer cells due to proliferative signaling involving c-Myc or cyclin D1 through the increase of eiF4E and CRM1 protein levels." (PMID 29495341, 2018). "For example many human tumors overexpress D-type cyclins and CCND1 represents the second most frequently amplified locus in the human cancer genome." (PMID 30322449, 2018). "Data show that gene-silencing hyper-methylation in the promoter region of CDKN2A or overexpression of CCND1 frequently occurs in several cancer types." (PMID 29492214, 2018). "Blocked NF-κB activity reduced cyclin E1 and cyclin D1 expression, which regulates cell cycles in various cancers through cell-cycle checkpoints, thus inhibiting the passage through the restriction point in late G138." (PMID 29531296, 2018). "Over-expression of cyclin D1 is commonly found in various types of cancers including breast, colon, liver and lung cancers." (PMID 30534074, 2018). "CCND1 is key driver of normal cell cycle regulation and genetic variation in this gene has been reported in many types of cancers." (PMID 30361291, 2018). "Specifically, CCND1 was identified in six individuals as the trunk gene and is a well-known cancer oncogene located on 11q13." (PMID 30540749, 2018). "Cyclin D1 has been thought to be oncogenic, and cyclin D1 overexpression was frequently observed in cancers." (PMID 30279365, 2018). "Nicely fitting with these data, we determined that in SkBr3 cancer cells and CAFs E2 and G-1 induce c-Fos and Cyclin D1 expression toward cell proliferation." (PMID 30423928, 2018). "Cyclin D1 has been frequently found deregulated in cancer and is regarded as a biomarker of invasive cancer phenotype." (PMID 29332262, 2018). "MiR‐365 plays roles in the initiation and development of cancers by repressing bcl‐2 and cyclin D1/cdc25A expression." (PMID 29451327, 2018). "Several studies have demonstrated that SFN causes G1/S and G2/M cell cycle arrest by altering the levels of cyclin A, cyclin B1, cyclin D1 and p21cip1/waf1 in cancer." (PMID 28864908, 2018). "Nuclear EGFR and Src play important roles in transcriptional co-activation of several cancer-promoting genes such as c-Myc and cyclin D1." (PMID 29641465, 2018). "Accumulating evidence suggests that mutations of the CCND1 gene that result in nuclear retention and constitutive activation of CDK4/6 kinases are oncogenic drivers in cancer." (PMID 29969496, 2018). "CCND1 acts as oncogene and is frequently overexpressed in a variety of cancers often via gene amplification or gene rearrangement." (PMID 29969496, 2018).